MROH2A (maestro heat like repeat family member 2A)
Synonyms: HEATR7B1
Tractability: No criterion of Open Targets' tractability assessment is met for any kind of drug.
Safety:
Unwanted effects reported when the protein is acted on. In parentheses: how it was acted on, where the effect was seen, and who reports it.
neutropenia (source: ClinPGx)
Gene: Protein-coding gene on chromosome 2 (233,775,679 to 233,833,423, forward strand). Ensembl gene ENSG00000185038.
Subcellular location (Human Protein Atlas): Cytosol
Gene Ontology:
Cellular component: cytoplasm
Genetic constraint (gnomAD): Loss-of-function variants: 152 observed, 169.54 expected, observed/expected ratio (o/e) 0.9, 90% interval 0.79 to 1.03. The upper end of that interval is the gene's LOEUF score, 1.03, which puts it in group 4 of 6, group 1 being the genes least tolerant of losing a copy. Missense variants: 1,837 observed, 1,933.5 expected, observed/expected ratio (o/e) 0.95, 90% interval 0.91 to 0.99. Synonymous variants: 763 observed, 768.75 expected, observed/expected ratio (o/e) 0.99, 90% interval 0.93 to 1.05.
Homologues: Orthologues: macaque MROH2A (96% identical), dog MROH2A (83% identical), pig MROH2A (82% identical), mouse Mroh2a (80% identical), rat Mroh2a (80% identical), rabbit MROH2A (76% identical), guinea pig MROH2A (75% identical), chimpanzee MROH2A (66% identical). Paralogues in human: MROH2B (28% identical), MROH1 (26% identical), MROH5 (15% identical), MROH7 (13% identical), MROH8 (11% identical), MROH6 (8% identical), MROH9 (8% identical), MRO (4% identical).
Diseases named in the same sentence as MROH2A in open-access papers:
MROH2A is named in the same sentence as 6 diseases in open-access papers, as found by Europe PMC text mining. Sharing a sentence is not in itself a finding about the gene and the disease. The quoted sentences say what the papers report.
Cirrhosis (1 paper, 2024). A chronic disorder of the liver in which liver tissue becomes scarred and is partially replaced by regenerative nodules and fibrotic tissue resulting in loss of liver function. "One example is the rs2361502:T allele in MROH2A, which is associated with a substantial increase in total bilirubin levels (β: .088), but has no obvious effect on cirrhosis risk (HR:1.02)." (PMID 39425533, 2024).
migraine (1 paper, 2020). "Of the five new migraine genes, two (MROH2A on chromosome 2q37.1, and PLCE1-AS1 on chromosome 10q23.33) were located at previously reported migraine loci." (PMID 32121467, 2020).
tumor (1 paper, 2023). "In contrast, we have not found sufficient bibliographic evidence to support the role of ANKRD24 and MROH2A in the tumor process." (PMID 37175550, 2023).
MROH2A also shares sentences with these, for which no sentence is quoted: cardiovascular diseases (1 paper); Obesity (1); tongue cancer (1).